LEP (leptin)
Diseases named in the same sentence as LEP in open-access papers (continued):
Sharing a sentence is not in itself a finding about the gene and the disease.
Hypertension (continued). "Higher preconception leptin concentrations were associated with an increased risk of GDM and hypertensive disorders including pre‐eclampsia, though not with PTD or pregnancy loss." (PMID 32313676, 2020). "Based on their results, the authors concluded that there was a lack of contribution of leptin to the development of hypertension and a lack of translatability of the results obtained in murine models." (PMID 31656583, 2019). "Vice versa, leptin is a potent stimulator of the sympathetic nervous system (SNS), and hyperleptinemia may contribute to hypertension in obese humans and rodents." (PMID 29675134, 2018). "Mergetpa reversed and normalized most of those alterations, but failed to affect leptin levels and hypertension." (PMID 28824433, 2017). "Noteworthy, HFHSu mice and HFD hypertension‐resistant mice, despite having elevated levels of leptin, did not develop hypertension, or featured elevated hypothalamic CART mRNA expression and CART‐positive neurones in DMH when compared to C diet." (PMID 27273815, 2016). "Leptin depletion in both animals and humans results in a quasi-MetS condition, but lacking essential hypertension and sympathetic hyperexcitability." (PMID 27147943, 2016). "For instance, leptin leads to the secretion of proinflammatory cytokines, such as TNF-α and IL-6, and to the generation of reactive oxygen species (ROS) in endothelial cells, both promoters of hypertension." (PMID 26064110, 2015). "The mechanisms by which hypertension/leptin or ROS induce vascular hypertrophy have not been fully elucidated yet." (PMID 26557089, 2015). "Plasma levels of leptin, in general, are higher in essential hypertensive patients (not obese) compared to controls." (PMID 26557089, 2015). "Leptin also regulates blood pressure via augmentation of renal sympathetic nerve activity (RSNA); events which are believed to play a significant role in the development of hypertension." (PMID 25152707, 2014). "However, the lack of success of human recombinant leptin infusions on weight loss in obese subjects, and adverse cardiovascular profile of hypertension, left ventricular dysfunction, and possible cardiovascular risk may need to be factored in for contemplating leptin route of BAT activation." (PMID 26937283, 2014). "Because our analysis was retrospective, some additional useful data such as coexisting hypertension, serum cholesterol, or other serum adipokines such as leptin and adiponectin which regulate insulin sensitivity were not recorded in the dataset." (PMID 23786836, 2013). "It was suggested that alteration in plasma levels of leptin, neuropeptide-Y and α-MSH (melanocyte-stimulating hormone) might be involved in activation of sympathetic activity that leads to hypertension in obese patients." (PMID 22812583, 2012). "Further biochemical analysis showed that with a hypertension phenotype, with and without DMT2, there was a positive association with adipokines such as leptin, leptin/adiponectin ratio, as well as TNF-α and ANG II." (PMID 23251471, 2012). "Another study had reported that leptin gene is not a major contributor of hypertension in African-Americans." (PMID 19772655, 2009). "Together, these data suggest that the leptin–endothelial axis may represent a broader physiological phenomenon relevant across cardiometabolic phenotypes rather than a relationship confined to hypertension." (PMID 41470134, 2025). "The authors concluded that leptin is not essential for adiposity-related hypertension to occur and that other mechanisms may be involved." (PMID 37872379, 2024). "An opposing argument is that adiposity-related hypertension is not dependent on leptin as BP does not increase with leptin administration in individuals with lipodystrophy (the absence of depot-specific or generalised subcutaneous adipose tissue) or congenital leptin deficiency." (PMID 37872379, 2024).
Hypertension (continued). "It has been demonstrated that leptin released by adipocytes stimulates the increase in SNA, which may fuel the mechanism development of obesity-related hypertension through sodium retention and also shows correlation between a high-fat diet and hypertension." (PMID 38727287, 2024). "Furthermore, increased leptin-mediated sympathetic nervous system activation may promote arteriosclerosis and CKD progression in the kidneys via hypertension." (PMID 37371050, 2023). "Likewise, a study comparing pregnant women without hypertension to those with mild preeclampsia and severe preeclampsia found increased cord blood leptin and decreased cord blood ghrelin in pregnancies affected by preeclampsia." (PMID 37764824, 2023). "However, the roles of exercise-induced changes in body composition, metabolic hormones (i.e., leptin and insulin) as well as their interactions with the RAS components and mediators of inflammation and oxidative stress in the sensitization of hypertension warrant further investigation." (PMID 35250473, 2022). "High leptin levels seem to correlate with left ventricular wall mass or wall thickness, independent of high blood pressure, indicating leptin may play a central role in the development of cardiomyopathy." (PMID 33495937, 2022). "This intersection analysis showed that the final list of shared genes among hypertension, NAFLD, fibrosis and inflammation contained only four genes, including LEP, ADIPOQ, AHR and TGFB1, which could be regarded as important genes related to hypertension and NAFLD." (PMID 34096467, 2021). "Leptin resistance may contribute to CAD, hypertension, and atherosclerotic disease." (PMID 34178553, 2021). "However, little research has been done on whether leptin and APN are also produced by VSMCs and whether their expression is affected by hypertension." (PMID 32566092, 2020). "On the one hand, some hormones such as adiponectin or leptin may exert effects on hypertension independent of BMI25,26." (PMID 29844414, 2018). "Moreover, chronic-stress and/or adiposity (and its metabolic by-products, such as leptin, LDL cholesterol or triglycerides) could affect the functionality (e.g., hypertension) and structure of blood vessels (e.g., atherosclerosis)." (PMID 29375342, 2017). "However, we used this model to study the effect of hypertension and leptin in an isolated setting without the effects of the central nervous system and the effects of leptin on the sympathetic nervous system." (PMID 27746739, 2016). "However, the mechanism by which hypertension increases plasma leptin levels is still not clear." (PMID 26557089, 2015). "Conversely, a different study reported lower cord blood leptin and IGF-1 levels in pregnancies affected by preeclampsia compared to those without hypertension." (PMID 37764824, 2023). "A possible explanation for the positive relationship of leptin with 24 h SBP and DBP, but not clinic BP, may be that 24 h ABPM is regarded as a superior measure to identify hypertension when compared to clinic BP." (PMID 37872379, 2024). "In the Inter99 study, we have previously found that leptin, but not adiponectin or CRP, may play a mediating role in overweight-induced hypertension." (PMID 26035431, 2015).
Hyperglycemia (374 papers, 2007 to 2026). An increased concentration of glucose in the blood. "Its deficiency, hyperglycemia and low leptin (due to lipoatrophy) that characterized T1DM, inhibit the expression of kisspeptin in hypothalamic neurons and blunt gonadotropin-releasing hormone (GnRH) release that lowers gonadotropin levels." (PMID 41237113, 2025). "Maternal adiposity is associated with increased leptin production, hyperinsulinemia, and hyperglycemia, leading to fetal hyperglycemia and excessive insulin secretion." (PMID 40243644, 2025). "The exacerbation of fed hyperglycemia by hepatic FASN ablation in leptin-deficient mice appeared attributable to impairment of hepatic glucose uptake triggered by hepatic glycogen accumulation and citrate-mediated inhibition of glycolysis." (PMID 37681411, 2023). "The exacerbation of fed hyperglycemia by FASN ablation in leptin-deficient mice appeared attributable to impairment of hepatic glucose uptake triggered by glycogen accumulation and citrate-mediated inhibition of glycolysis." (PMID 37681411, 2023). "Our results suggested that, in NCD-fed ob/ob HKO mice, the exacerbated hyperglycemia in the fed state is attributable to leptin deficiency–dependent glucose overfeeding, whereas the hypoglycemic phenotype is independent of leptin deficiency." (PMID 37681411, 2023). "The abnormal activation of these neurons due to energy deficiency as the neural basis for T1DM hyperglycemia and leptin action is mediated by inhibiting these neurons across withdrawing energy deprivation." (PMID 36674935, 2023). "It is common knowledge that the more WAT, the more leptin is produced, causing peripheral hyperleptinemia and central hypoleptinemia, resulting in hyperglycaemia, hyperinsulinemia, hyperlipidaemia, and inflammation." (PMID 37046893, 2023). "Investigation of LEP (rs7799039) gene polymorphism revealed that the GA genotype was associated mostly with the development of MS, since it was associated with hyperglycemia and hypercholesterolemia." (PMID 36117520, 2022). "Leptin deficiency in BTBR strain is a key mechanism for the acceleration of hyperglycemia-associated damage, indicating the importance of the genetic background as responsible for the modification of the diabetic phenotype." (PMID 35409324, 2022). "Since leptin action on reducing T1D hyperglycemia is known to be associated with restraining counter-regulatory hormone levels, we tested the effect of leptin i.c.v infusion on fasting responses." (PMID 33976218, 2021). "Leptin can rescue hyperglycemia in type 1 diabetes, but the underlying mechanisms for this effect are not clear." (PMID 33976218, 2021). "Particularly, in the specific knock—out of Socs3 in SF1 neurons, where leptin signaling is over-activated, Ren Zhang and colleagues observed improved glucose homeostasis, showing protection against hyperglycemia and hyperinsulinemia caused by HFD feeding." (PMID 34201257, 2021). "In our recording experiments, we focused on LepRArc neurons that were inhibited by leptin, as these neurons are presumed to be the most relevant to T1D hyperglycemia due to their heightened activity associated with low leptin levels." (PMID 33976218, 2021). "Conversely, specific inhibition of GABAArc neurons causes a leptin-mimicking effect on reducing T1D hyperglycemia, while inhibiting AgRP neurons has a much more attenuated effect." (PMID 33976218, 2021). "T1D models exhibit a severe reduction of leptin levels, suggesting a physiologic contribution of leptin loss toward uncontrolled hyperglycemia in T1D." (PMID 33976218, 2021). "When fetuses were studied at 10 and 25 days after surgery, pancreatectomy caused hypoinsulinaemia, hyperglycaemia and growth retardation which was associated with low plasma concentrations of leptin and a marker of osteoclast activity and collagen degradation." (PMID 34708692, 2021).
Hyperglycemia (continued). "Central leptin action rescues type 1 diabetic (T1D) hyperglycemia; however, the underlying mechanism and the identity of mediating neurons remain elusive." (PMID 33976218, 2021). "T1D exhibits a severe reduction in leptin levels, suggesting a significant contribution of loss of brain leptin action to the pathogenesis of T1D hyperglycemia." (PMID 33976218, 2021). "Changes in fetal DNA methylation (DNAm) of the leptin (LEP) gene have been associated with exposure to maternal hyperglycemia, but their links with childhood obesity risk are still unclear." (PMID 31947745, 2020). "Leptin treatment ameliorates hyperglycemia in rodents with insulin deficiency, an effect that is independent of food intake and glucose loss in urine." (PMID 31743040, 2020). "Surprisingly, the survival rate of insulin-deficient RIP-CreΔLEPR mice administered leptin (RIP-CreΔLEPR-LEP) was comparable to insulin-deficient WT mice administered leptin (WT-LEP) despite hyperglycemia." (PMID 33071988, 2020). "As expected, leptin therapy improved the hyperglycemia and hyperketonemia caused by ID in Tlr4+/+ controls; yet, similar outcomes were observed in insulin deficient Tlr4−/− mice." (PMID 31391467, 2019). "Infusion of recombinant leptin for seven days is sufficient to ameliorate hyperglycemia and hyperinsulinemia in leptin-deficient ob/ob mice." (PMID 31718027, 2019). "In this sense, deletion of iNOS in leptin-deficient ob/ob mice improves hyperglycemia, hyperinsulinemia, and insulin resistance." (PMID 31500090, 2019). "Metabolic rate, glycolytic activity and leptin increase during periods of hyperglycemia associated with acute osmoregulatory stress as well as during tumorigenesis." (PMID 30186233, 2018). "We previously showed that ghrelin inhibits glucose-induced insulin secretion, and ghrelin ablation improves hyperglycemia of leptin-deficient mice." (PMID 28420089, 2017). "We selected cord blood leptin levels considering that our previous results showed that maternal hyperglycemia is closely linked to cord blood leptin levels." (PMID 27340502, 2016). "They found that systemic overexpression of leptin ameliorates hyperglycemia in a near-complete insulin-deficient mouse model." (PMID 25870537, 2015). "We have reported earlier that exogenous leptin can normalize hyperglycemia in diabetic, obese and leptin-deficient Lepob/ob mice (ob/ob) independently of changes in body weight and caloric intake." (PMID 26500840, 2015). "To confirm our findings from the DIO mouse experiment, we tested the effect of CEF on hyperglycemia in the rat ZDF model which has a leptin gene deficiency (lep-/lep-)." (PMID 26709835, 2015). "Similar results were obtained in the present study: serum leptin levels were significantly associated with abdominal obesity (AO), hypertriglyceridemia, and hyperglycemia." (PMID 24981337, 2014). "In 2008, Unger and colleagues reported that leptin overexpression is capable of rescuing the sever hyperglycemia and lethality brought on by insulin deficiency in rodents." (PMID 24589844, 2014). "An interruption of hepatic metabolism of glucose, fatty acids, and lipoproteins in the leptin-deficient obese (Lepob/ob) mouse leads to hyperglycemia, steatosis, and hypercholesterolemia." (PMID 23634778, 2013). "Intracerebroventricular (icv) infusion of leptin reverses and greatly improves hyperglycemia, hyperglucagonemia, hyperketonemia, and polyuria caused by insulin deficiency in mice." (PMID 23579596, 2013). "The main underlying mechanisms involve persistent hyperglycemia hyperinsulinemia and leptin resistance." (PMID 23227034, 2012). "Studies involving recombinant leptin administration in ob/ob deficient mice, which lack endogenous leptin, demonstrate significant reductions in food intake and body weight, primarily through decreased adiposity and improved hyperglycemia." (PMID 41226331, 2025).
Hyperglycemia (continued). "Research using streptozotocin-treated mice characterized by severe insulin deficiency exhibited uncontrolled hyperglycemia resulting in a catabolic state with lower serum leptin levels, which inhibit the kisspeptin expression in central nervous system, a crucial stimulator of GnRH." (PMID 40110863, 2025). "Early studies demonstrated that hyperglycemia in leptin-deficient mice could be restored with exogenous leptin treatment." (PMID 41251447, 2025). "In STZ-induced T1DM rodent models, insulin deficiency and the uncontrolled hyperglycemia reach catabolic state characterized by low leptin levels, lipolysis and secretion of free fatty acids that move to the liver for triglycerides and LDL-cholesterol production." (PMID 41237113, 2025). "In addition, male androgen hormones were implicated due to their ability to suppress leptin secretion, which increased the rate of consumption of WR and led to persistent hyperglycaemia." (PMID 36677591, 2023). "Maternal hyperglycaemia was associated with DNA methylation of the leptin gene, which could risk childhood obesity." (PMID 37854189, 2023). "Several lines of studies have shown that central infusion of leptin is able to normalize hyperglycemia in rodents with severe insulin-deficient diabetes for couples of days, and this ameliorative effect is achieved through an insulin-independent increase of glucose disposal." (PMID 35619170, 2022). "Interestingly, altered methylation of the peroxisome proliferator-activated receptor-γ co-activator 1 α (PPARGC1A) gene mediated the association between maternal hyperglycemia and the cord blood leptin levels." (PMID 34946940, 2021). "Despite potent effects of leptin action on reducing T1D hyperglycemia, the underlying cellular mechanism remains unclear." (PMID 33976218, 2021). "Many studies reported that leptin promoters were hypermethylated in the placentas of obese mothers leading to decreased placental leptin expression while leptin deficiency is associated with hyperglycemia both in humans and animals." (PMID 34828259, 2021). "Further delineation of the functional identity of these neurons in their underlying neural pathway may reveal new insights on leptin action on reducing T1D hyperglycemia." (PMID 33976218, 2021). "In addition, our association between LEP DNAm and maternal hyperglycemia as a marker of childhood fat distribution seemed to be independent of neonatal leptinemia." (PMID 31947745, 2020). "When examining MetS components separately, we observed higher odds of abdominal obesity and hyperglycemia associated with leptin in both men (15.19 (7.04, 32.79)) and (15.14 (5.64, 40.62)), respectively) and women (2.08 (1.45, 2.98) and 1.97 (1.01, 3.82), respectively)." (PMID 33374992, 2020). "We have shown before that maternal hyperglycemia is associated—and may be causally implicated—with changes in neonatal offspring DNAm levels at the leptin gene (LEP)." (PMID 31947745, 2020). "We hypothesized that change in plasmatic protein(s) content could underlie re-emergence of hyperglycemia following decrease-of-leptin action (i.e. leptin withdrawal)." (PMID 31391467, 2019). "The hyperglycaemia in leptin-deficiency impairs the host system to clear the bacteria from liver but leptin therapy may corrected the blood glucose levels by increasing insulin sensitivity and improved host resistance to this bacterial infection." (PMID 29868503, 2018). "In addition, our mediation analyses support that epigenetic regulation of PPARGC1α is implicated in the link between maternal hyperglycemia and elevated cord blood leptin levels, considered as a marker for adiposity in offspring." (PMID 27340502, 2016). "Leptin in supraphysiological doses in vitro is known to block insulin interaction with its receptor on the cell membrane, which is associated with impaired insulin-mediated glucose transport, hyperglycaemia and more severe IR." (PMID 24433403, 2014).